KRAS (KRas proto-oncogene, GTPase)
Diseases named in the same sentence as KRAS in open-access papers (continued):
Sharing a sentence is not in itself a finding about the gene and the disease.
tumor (continued). "In this paper, we described the development and analytical validation of a custom designed, multiplexed mutation assay to detect 35 mutations of interest in KRAS, BRAF, and NRAS genes in FFPE tumor tissue for patient stratification in clinical trials." (PMID 23991070, 2013). "This mutation (chromosome 12) is present in over 90% of PDAC, and involves the highest fraction of KRAS alteration found in any human tumor type." (PMID 24084722, 2013). "In the mutant KRAS subpopulation, 2/8 patients (25%) were identified with SD and showed a significant decrease in tumor marker expression." (PMID 24137455, 2013). "Chen and colleagues noted an inverse correlation in KRAS protein levels in relation to miR-143 expression and a possible role of miRNAs in a tumor suppressor effect." (PMID 23091478, 2012). "The concordance rates of the KRAS status between primary tumor sites and paired metastatic organs were also analyzed." (PMID 22876814, 2012). "Antibodies against the epidermal growth factor receptor (EGFR), cetuximab and panitumumab, have shown a survival benefit in mCRC patients with KRAS wild-type tumours both as monotherapy and when added to chemotherapy." (PMID 22804917, 2012). "A discordant KRAS status between primary tumour and metastatic tissues was observed in a small number of patients (3.6%)." (PMID 23226727, 2012). "Increased AURKA-CN is common in mCRC tumours and is associated with longer OS and longer PFS during chemotherapy, particularly in KRAS wild-type tumours." (PMID 22240781, 2012). "In the XELOX plus bevacizumab maintenance group, median PFS was 12.6 months versus 10.0 months in patients with WT and MT KRAS tumours, respectively (p = 0.0560; HR: 1.39; 95% CI: 0.99–1.95)." (PMID 23174912, 2012). "Baseline characteristics of patients included in the KRAS analysis according to tumour KRAS status (n = 394)." (PMID 23174912, 2012). "In our series, CDKN2A methylation positivity correlated with more frequent right-sided disease, mucinous histology, tumor grade as well as with MSI, BRAF mutation and with KRAS mutation in the MSI setting only." (PMID 22925370, 2012). "Addition of epidermal growth factor receptor (EGFR)-targeted agents (e.g. the chimeric antibody cetuximab or the fully human antibody panitumumab) to FOLFIRI also significantly improves outcomes in patients with wild-type (WT) KRAS tumours." (PMID 23020584, 2012). "A KRAS mutation was demonstrated in the primary tumour of 15 patients (6 good responders and 9 poor responders), and KRAS wild-type in the primary tumour of 19 patients (11 good responders and 8 poor responders)." (PMID 22804917, 2012). "Patients with KRAS wild-type tumours were randomly assigned (1:1) to receive panitumumab (6 mg/kg; every 2 weeks with the first 6 weeks of chemotherapy) or not." (PMID 23017669, 2012). "MiR-143 is thought to inhibit KRAS translation and thereby to suppress tumour cell growth during tumourigenesis." (PMID 22804917, 2012). "The improved OS for patients with high AURKA-CN was most pronounced in our study among patients with KRAS wild-type tumours." (PMID 22240781, 2012). "The authors also noted that the benefit of treatment was greater in patients with WT compared with MT KRAS tumours." (PMID 23174912, 2012). "In our study, 49.8% of patients with WT KRAS tumours received an anti-EGFR agent after bevacizumab treatment." (PMID 23174912, 2012). "More patients in the WT KRAS group had eye toxicities compared with the MT group (45% vs. 29%) whereas more patients with MT KRAS tumours experienced hair (31% vs. 51%) and nail (29% vs. 37%) toxicities." (PMID 23020584, 2012). "The role of miR-143 as a tumor suppressor was demonstrated through the ability of miR-143 inhibition to increase KRAS protein levels and cell proliferation in vitro." (PMID 23202889, 2012).
tumor (continued). "Among patients with KRAS wild-type tumours, those with high AURKA-CN tumours had prolonged PFS compared with patients with low AURKA-CN tumours (HR=0.43, 95% CI: 0.19–0.94, P=0.04)." (PMID 22240781, 2012). "In our study, qRT-PCR analysis showed SHC4 (15.85-fold), SOS2 (2.78-fold), CCDC6 (6.18-fold), and KRAS (5.92-fold) were up-regulated significantly in tumor tissues." (PMID 23285163, 2012). "The improved response of patients with KRAS wild-type tumours treated with anti-EGFR therapy has been well documented in the literature." (PMID 22240781, 2012). "Median PFS was 10.9 months for patients with WT KRAS and 9.4 months for patients with MT KRAS tumours (p = 0.0038; HR: 1.40; 95% CI:1.12–1.77)." (PMID 23174912, 2012). "Patients with WT KRAS tumours had a significantly greater clinical benefit than those with MT KRAS tumours in terms of ORR (57.5% versus 43.4%), PFS (10.9 versus 9.4 months) and OS (26.7 versus 18.0 months)." (PMID 23174912, 2012). "We have found that cells with mutant KRAS produce exosomes containing tumor-promoting proteins including mutant KRAS itself." (PMID 26082068, 2012). "Retrospective analyses have shown that bevacizumab in combination with irinotecan/5-fluorouracil (5-FU)/leucovorin chemotherapy provides a significant clinical benefit for patients with mutant (MT) and wild-type (WT) KRAS tumours." (PMID 23174912, 2012). "The concordance rate (87.7%) of the KRAS mutation status at metastatic sites other than the lung was generally high compared with primary tumor sites; however, lung metastasis had a high rate of KRAS discordance (32.4%)." (PMID 22876814, 2012). "This analysis of the MACRO study suggests a prognostic role for tumour KRAS status in patients with mCRC treated with XELOX plus bevacizumab." (PMID 23174912, 2012). "Of the KRAS wild-type patients, 4 had a BRAF mutated tumour (1 good responder and 3 poor responders)." (PMID 22804917, 2012). "A total of 47 patients (11.9%) underwent salvage surgery of metastases, 28 of whom had WT KRAS tumours and 19 had MT KRAS tumours (p = 0.5574)." (PMID 23174912, 2012). "The present analysis of the MACRO study indicates that tumour KRAS status is a prognostic factor in patients with mCRC receiving bevacizumab in combination with capecitabine plus oxaliplatin." (PMID 23174912, 2012). "In the multivariate analysis, KRAS status, primary tumor site, and clinical situations for the development of systemic metastasis were significant predictors for liver-only and/or lung-only metastases." (PMID 22876814, 2012). "Copy number loss of the KRAS locus was restricted to good responders, whereas a copy number gain was associated with a poor PFS in patients with wild-type KRAS tumours." (PMID 22804917, 2012). "Specifically, KRAS, BRAF and PIK3CA mutations were detected in 10 (45%), 3 (14%) and 2 (9%) tumor specimens, respectively." (PMID 23144797, 2012). "The goal in this study was to assess the frequency of increased AURKA-CN in archival tumour tissues of patients with metastatic CRC (mCRC) and correlate this finding with progression-free survival (PFS), overall survival (OS), and KRAS mutation status." (PMID 22240781, 2012). "The full coding sequences and intron-exon junctions of the KRAS gene were sequenced in the entire series of 478 CRC patients; KRAS mutations were detected in 145 (30%) primary tumours (one patient had two mutations, G12D and Q61L)." (PMID 22931052, 2012). "In the single-agent bevacizumab group, median PFS was 10.8 versus 8.7 months in patients with WT and MT KRAS tumours, respectively (p = 0.0492; HR: 1.38; 95% CI, 1.00–1.89)." (PMID 23174912, 2012). "KRAS contains multiple let-7 complementary sites, allowing the let-7 family of miRNAs to act as a tumour suppressor by regulating the KRAS mRNA." (PMID 22804917, 2012). "As expected, the KRAS signaling pathway was the most heavily impacted pathway (P<0.05), along with tumor-stroma interactions and tumor suppressive pathways." (PMID 23071490, 2012).
tumor (continued). "If FOLFOX or CapeOx based therapies are used as first-line, FOLFIRI, with or without cetuximab or panitumumab (KRAS wild type tumor only), and irinotecan in combination with cetuximab (KRAS wild type tumor only) or as a single agent is recommended." (PMID 22716038, 2012). "In this study, consistently favourable efficacy was observed in patients with WT vs. mutant (MT) KRAS tumours." (PMID 23020584, 2012). "In conclusion, although KRAS and FGFR2 mutations share similar activation of the MAPK pathway, our data suggest very different roles in tumor biology." (PMID 22383975, 2012). "One patient with tissues acquired from a primary tumor (colon) and related pancreatic metastatic site showed concordance of KRAS status (KRAS mutant; Gly12Cys)." (PMID 22876814, 2012). "Cetuximab did not appear in recommendations until 2009, when it was recommended for use in patients with wild-type KRAS tumours." (PMID 21848897, 2012). "Both of these receptors activate the KRAS signalling pathway, which in turn is also commonly up-regulated in these tumours." (PMID 22536405, 2012). "We undertook an analysis of data from the MACRO study to evaluate the prognostic value of tumour KRAS status in patients receiving combination therapy with capecitabine plus oxaliplatin (XELOX) and bevacizumab." (PMID 23174912, 2012). "Both EGFR and KRAS mutations were present more commonly in ADC compared to SCC and other tumor types." (PMID 22528563, 2012). "The confirmed ORR was 57.5% in patients with WT KRAS tumours compared with 43.4% in patients with MT KRAS tumours (p = 0.0054; OR: 1.77, 95% CI 1.18–2.64)." (PMID 23174912, 2012). "Median OS was 28.0 months in patients with WT KRAS tumours who received post-study anti-EGFR therapy versus 20.2 months in those with MT KRAS tumours (HR: 1.68; 95% CI: 1.25–2.26; p = 0.0006)." (PMID 23174912, 2012). "Although the larger cluster of 47 samples (Cluster-Group 1; open squares) consisted of 26 (55%) KRAS/BRAF wild-type tumors, KRAS/BRAF wild-type and mutated cases were equally distributed within the two tumor clusters (P = 0.17)." (PMID 23226389, 2012). "For chemoresistant mCRC, cetuximab or panitumumab are recommended as monotherapy in patients with wild-type KRAS tumours." (PMID 21848897, 2012). "The emergent knowledge of molecular tumor profiles e.g., EGFR and KRAS mutations and ALK rearrangements for instance raises logistic and algorithmic considerations to approaching the molecular management of the adenocarcinoma subtype of NSCLC." (PMID 25562798, 2012). "Wild-type (WT) KRAS tumours were found in 219 patients (56%) and mutant (MT) KRAS in 175 patients (44%)." (PMID 23174912, 2012). "We also observed high detection concordance for critical ‘hot-spot’ mutations (KRAS, BRAF, PIK3CA) in matched cpDNA and archival tumor tissue, and important differences between archival tumor and cpDNA." (PMID 23144797, 2012). "The prognostic value of tumour KRAS status has been extensively evaluated in patients with advanced and localised CRC, although results have been conflicting." (PMID 23174912, 2012). "Of these tumours one sample contained a gain of the complete p-arm of chromosome 12 and the other sample contained a high copy number gain of a region including the KRAS locus." (PMID 22804917, 2012). "Factors influencing KRAS test results in tumor specimens include: tumor heterogeneity, sample handling, slide preparation, techniques for tumor enrichment, DNA preparation, assay design and sensitivity." (PMID 22534075, 2012).
tumor (continued). "A statistically significant difference was observed in OS: patients with WT KRAS tumours had a median OS of 26.7 months versus 18.0 months for patients with MT KRAS tumours (p = 0.0002; HR: 1.55; 95% CI: 1.23–1.96)." (PMID 23174912, 2012). "Responses were observed in 126 patients (57.5%) with WT KRAS tumours and 76 patients (43.4%) with MT KRAS tumours (p = 0.0054; OR: 1.77; 95% CI: 1.18–2.64)." (PMID 23174912, 2012). "Mean (SE) baseline scores for responding patients vs. progressing patients with WT KRAS tumours were 0.81 (0.03) vs. 0.72 (0.18), respectively; mean scores in responding vs. progressing patients with MT KRAS tumours were 0.82 (0.05) vs. 0.59 (0.20)." (PMID 23020584, 2012). "Both KRAS and PIK3CA mutations were evaluated for association with several pathological parameters: sex, age at diagnosis, anatomical location of primary CRC, tumour grading, AJCC stage of the disease." (PMID 22931052, 2012). "For chemoresistant mCRC, European guidelines also recognized the effectiveness of cetuximab or panitumumab as single agents, or irinotecan plus cetuximab, in patients with wild-type KRAS tumours." (PMID 21848897, 2012). "Resection was complete (R0) in 20 patients (71.4%) with WT KRAS and 12 (63.2%) with MT KRAS tumours (p = 0.0769)." (PMID 23174912, 2012). "Sixty-one mCRC tumours were analysed for AURKA-CN using q-PCR, and KRAS mutation status by direct sequencing." (PMID 22240781, 2012). "Median PFS was significantly longer in patients with WT versus MT KRAS tumours, 10.9 months versus 9.4 months (p = 0.0038; HR: 1.40; 95% CI: 1.12–1.77)." (PMID 23174912, 2012). "Both copy number gains, which were confirmed by MLPA, were observed in poor responders with a KRAS wild-type tumour." (PMID 22804917, 2012). "By using a TaqMan-based KRAS copy number assay, KRAS amplifications were observed in approximately 2% of the 106 investigated colorectal primary tumours." (PMID 22804917, 2012). "There appeared to be a trend for better tumour response in patients with higher baseline health state index scores in both the WT and MT KRAS groups." (PMID 23020584, 2012). "Specifically, increased expression of KRAS mRNA was found in 52 (43 %) tumor tissues, while the increased expression of KRAS protein was found in 54 (45 %) tumor tissues." (PMID 22537942, 2012). "Compared with primary tumor sites, the KRAS discordance rate was significantly higher in matched lung metastases [32.4% (12/37)] than in other matched metastatic organs (P = 0.005)." (PMID 22876814, 2012). "Researchers have shown that miR-143 functions as a tumor suppressor through inhibition of KRAS translation and that down-regulation of miR-143 drives tumor progression toward malignancy." (PMID 23091478, 2012). "They found that 8 of 9 patients, all of whom were radically treated, still displayed tumour-derived KRAS mutants in their plasma on day 3 after surgical resection." (PMID 23226727, 2012). "The difference was apparent in the survival curves for patients with WT KRAS tumours who received anti-EGFR, those with WT KRAS tumours who did not receive an anti-EGFR agent and patients with MT KRAS tumours." (PMID 23174912, 2012). "An additional retrospective analysis was performed to define the prognostic value of tumour KRAS status on progression-free survival (PFS), overall survival (OS) and response rates." (PMID 23174912, 2012). "We retrospectively analyzed objective tumor response rate, (ORR) progression-free (PFS) and overall survival (OS) with respect to the mutational status of KRAS, BRAF, PIK3CA and PTEN expression in mCRC patients treated with a cetuximab-based regimen." (PMID 22569004, 2012). "KRAS mutant patients (20% of available tumor samples) showed a RR of 8% with paclitaxel-carboplatin plus erlotinib, compared with 23% for patients that received the chemotherapy doublet alone." (PMID 21444946, 2011).
tumor (continued). "TTP and OS to the ≥2nd line cetuximab-containing treatment according to KRAS, BRAF, PIK3CA mutations status, PTEN protein expression, AREG and EREG mRNA expression and grade of skin rash in the KRAS WT patients′ population." (PMID 21283802, 2011). "KRAS mutation testing of all lymph nodes separately revealed overall concordant KRAS status between lymph node metastases and the primary tumour in three patients." (PMID 21364579, 2011). "BRAF mutations were mutually exclusive with KRAS mutations, and four BRAF mutations were found in tumours with MSI." (PMID 21901162, 2011). "Preclinical studies have suggested that RAS mutation would lead to radioresistance, and conversely that targeting RAS or downstream effectors of activated KRAS would identify potential tumor-specific radiosensitizers." (PMID 21910869, 2011). "One third of the patients with wt-KRAS or mt-BRAF tumour still respond to the treatment ̧ alluding that the BRAF status is not predictive for the response to anti-EGFR antibody therapy." (PMID 22933967, 2011). "Based on these findings, the European Medicines Agency and the US Food and Drug administration have placed restrictions on the usage of EGFR-targeted drugs and only approved for CRC metastatic patients with wild-type KRAS tumours." (PMID 21673680, 2011). "In PAC, the predictive value of KRAS mutations and EGFR amplification for erlotinib efficacy has been assessed from tumor samples of 26% of patients included in the prospective randomized Phase III trial." (PMID 24212636, 2011). "Of these, 243 patients had wild-type KRAS tumours (panitumumab+BSC, n=124; BSC alone, n=119) and were included in the Q-TWiST analyses." (PMID 21610704, 2011). "In the current study, we compared allele-specific qPCR assays for the most frequent activating mutations in EGFR, KRAS, BRAF and PIK3CA in tumor-positive fine needle cytological aspirates against histological material of primary tumors." (PMID 21408138, 2011). "Because of this, some clinicians have called for a reassessment of KRAS mutation status on metastatic foci in situations where only the primary tumor was assessed for KRAS status." (PMID 21437184, 2011). "Data obtained by detecting 145 and 73 bp KRAS amplicon confirmed the increase of ctDNA concentration with tumour weight observed in HT29 cells by detecting 133 bp ACTB amplicon." (PMID 21909401, 2011). "The EGFR pathway signals through Kras/Braf and although EGFR/c-Erb-B2 amplifications are rare in CRC, gain-of-function mutations in KRAS/BRAF are extremely common and are seen in up to 60% of tumours." (PMID 21698197, 2011). "On the other hand, the ctDNA concentrations obtained using the KRAS 145 primer set seemed to slightly increase with tumour size." (PMID 21909401, 2011). "In averaged copy number charts, KRAS mutant tumours showed a predilection for losses of 1p36.32-p13.2, 6q11.1-q27, 11p13-11q13.2 and 11q21-12p13.1 and gains of 1q21.1-q43." (PMID 21385341, 2011). "In conclusion, we studied the prevalence of PIK3CA, RAS (KRAS, NRAS), and BRAF mutations in diverse tumor samples and identified a high frequency of coexisting PIK3CA and BRAF or RAS mutations." (PMID 21829508, 2011). "In our analysis, using utility scores based on EQ-5D assessments collected during the phase 3 study, patients with wild-type KRAS tumours receiving panitumumab+BSC compared with patients on BSC alone had 6.5 more quality-adjusted weeks for PFS." (PMID 21610704, 2011). "Patients whose tumours were characterized by ligands' downregulation behaved like KRAS mutants upon treatment with anti-EGFR moAbs." (PMID 21283802, 2011). "Three tumour samples had KRAS genetic alterations suggesting therapeutic opportunity for treatment with MEK inhibitors." (PMID 21781349, 2011).